DCAF16 (DDB1 and CUL4 associated factor 16)
Description:
Functions as a substrate recognition component for CUL4-DDB1 E3 ubiquitin-protein ligase complex, which mediates ubiquitination and proteasome-dependent degradation of nuclear proteins.
Synonyms: C4orf30; FLJ20280
Tractability: Small molecule: a structure with a bound ligand is known. Antibody: the Human Protein Atlas places it where antibodies can reach. PROTAC: ubiquitination databases record sites on it; its protein half-life has been measured.
Gene: Protein-coding gene on chromosome 4 (17,793,446 to 17,810,758, reverse strand). Ensembl gene ENSG00000163257.
Subcellular location: Nucleus
Subcellular location (Human Protein Atlas): Cytosol; Plasma membrane
Pathways (Reactome):
Metabolism of proteins: Neddylation
Gene Ontology:
Molecular function: protein binding
Biological process: epigenetic regulation of gene expression; protein ubiquitination
Cellular component: Cul4-RING E3 ubiquitin ligase complex; nucleus; Cul4A-RING E3 ubiquitin ligase complex; Cul4B-RING E3 ubiquitin ligase complex; nucleoplasm
Genetic constraint (gnomAD): Loss-of-function variants: 11 observed, 18.49 expected, observed/expected ratio (o/e) 0.59, 90% interval 0.37 to 0.99. The upper end of that interval is the gene's LOEUF score, 0.99, which puts it in group 4 of 6, group 1 being the genes least tolerant of losing a copy. Missense variants: 249 observed, 261.04 expected, observed/expected ratio (o/e) 0.95, 90% interval 0.86 to 1.06. Synonymous variants: 111 observed, 98.82 expected, observed/expected ratio (o/e) 1.12, 90% interval 0.96 to 1.32.
Homologues: Orthologues: chimpanzee DCAF16 (100% identical), macaque DCAF16 (99% identical), rabbit DCAF16 (97% identical), dog DCAF16 (94% identical), pig DCAF16 (66% identical).
Diseases named in the same sentence as DCAF16 in open-access papers:
DCAF16 is named in the same sentence as 7 diseases in open-access papers, as found by Europe PMC text mining. Sharing a sentence is not in itself a finding about the gene and the disease. The quoted sentences say what the papers report.
type 1 diabetes (1 paper, 2014). "For example, we found that rs11171739, which is associated to type 1 diabetes, is a trans-eQTL of DCAF16, as previously shown in monocytes and is also a trans-eQTL of BEND4." (PMID 25010687, 2014).
uterine corpus endometrial carcinoma (1 paper, 2021). A endometrial carcinoma (disease) that involves the body of uterus. "The last example RES occurs in DCAF16 at chr4:17,804,740 in uterine corpus endometrial carcinoma (UCEC) (adjust p = 0.0137)." (PMID 34319007, 2021).
cancer (2 papers, 2016 to 2022). A tumor composed of atypical neoplastic, often pleomorphic cells that invade other tissues. "Previous study showed that the non-synonymous RNA-editing sites in AZIN1 (A1099G, ENST00000347770) and DCAF16 (A486G, ENST00000382247) are clinically relevant in cancers." (PMID 27687780, 2016).
DCAF16 also shares sentences with these, for which no sentence is quoted: adenocarcinoma (1 paper); neurodegenerative disease (1); squamous cell carcinoma (1); urothelial carcinoma (1).